HCP5 (HLA complex P5)
Diseases named in the same sentence as HCP5 in open-access papers (continued):
Sharing a sentence is not in itself a finding about the gene and the disease.
tumor (51 papers, 2017 to 2025). "It downregulated several potential oncogenes (e.g., AEBP1, MIAT) and genes linked to GBM proliferation and migration (e.g., SOCS2, HCP5) while modulating Wnt signaling and up-regulating tumor suppressor genes (e.g., SPRY4, BEX2)." (PMID 39874307, 2025). "Our findings indicated that the upregulation of LGALS3 via the HCP5/hsa-miR-27b-3p axis is associated with unfavorable prognosis and increased tumor immune infiltration in HCC." (PMID 38643145, 2024). "And further analysis of clinical characteristics suggested that the HCP5 level was significantly associated with tumor size." (PMID 35399723, 2022). "To further explore the potential prognostic value of HCP5, we evaluated the association between up-regulated HCP5 and tumor types." (PMID 34923990, 2021). "Collectively, most studies suggested that HCP5 is more frequently acting as an tumor oncogene in various malignancies, and associated with the prognosis and clinicopathological characteristics." (PMID 34923990, 2021). "Meanwhile, only one study reported that downregulation of HCP5 was associated with a poor prognosis, advanced tumor stage, positive distal metastasis and lymph node metastasis." (PMID 34923990, 2021). "Therefore, increased levels of HOXA7 and HCP5 were associated with the downregulation of tumor brain metastasis." (PMID 35693013, 2022). "During the last two decades, HCP5 SNPs have been associated with many different diseases in genome-wide association studies (GWASs), gene expression studies, and cancer studies investigating tissue and cellular biomarkers of tumor progression and inhibition." (PMID 31137555, 2019). "Based on these findings, we can conclude that the anti-tumor effect of TGR5 activation in the CC xenograft was partially achieved via modulating the HCP5/miR-139-5p/DDIT4 axis in vivo." (PMID 39201624, 2024). "The results of the immunohistochemical assay also confirmed that HCP5 was upregulated in malignant tumor tissues compared to paracarcinoma tissues and benign tumor tissues." (PMID 38071681, 2024). "Compared to the control group, the efficient knockdown of HCP5 resulted in a significant reduction in tumor volume and weight." (PMID 39201624, 2024). "In the xenograft model established with SKOV-3 cells, the number of lung metastases, tumor growth, and Ki67 expression in tumor tissues were markedly decreased by the knockdown of HCP5, accompanied by an increased percentage of TUNEL-positive cells." (PMID 38071681, 2024). "Compared to that in benign tumor tissues, the HCP5 level was markedly increased in malignant tumor tissues of OC patients and slightly changed in paracarcinoma tissues of OC patients." (PMID 38071681, 2024). "To evaluate the potential function of HCP5 in the TGR5 activation-induced anti-tumor effect, we upregulated the HCP5 expression in CC cells using the HCP5 overexpression plasmid." (PMID 39201624, 2024). "Murine xenograft studies demonstrated that TGR5 suppressed the tumor formation of CC cells and downregulated HCP5 and DDIT4 while increasing miR-139-5p in the xenografts." (PMID 39201624, 2024). "The fluorescence intensity of Ki67 in tumor tissues was found to be significantly reduced by HCP5 silencing." (PMID 38071681, 2024). "HCP5 knockdown notably restrained CC cell proliferation, colony formation, and migration in vitro, and inhibited tumor growth in vivo." (PMID 39201624, 2024). "A BALB/c nude mouse subcutaneous tumor model was constructed with Ctrl, HCP5‐132aa KO, KO+HCP5‐132aa, and KO+HCP5‐132aa mut GC cells." (PMID 39447131, 2024). "Collectively, these findings suggested that HCP5 enhances CC cell proliferation and migration, and promotes tumor growth in vivo, thus contributing to CC progression." (PMID 39201624, 2024). "Subsequently, HCP5 expression was validated by qRT–PCR assay of tumor and adjacent normal tissues from 5 HCC patients." (PMID 38643145, 2024).
tumor (continued). "Our xenograft results also showed that knockdown of the HCP5-132aa ORF inhibited tumor growth in vivo, similar to the effects of Erastin injection." (PMID 36980766, 2023). "We found that the expression level of HCP5 was significantly correlated with tumor size (P = 0.0041)." (PMID 35399723, 2022). "Taken together, silencing of HCP5 controlled tumor progression by inhibiting tumor progression in NPC cells." (PMID 35602292, 2022). "The decreased expression of HCP5 and increased expression of miR-128-3p were observed in tumor tissues." (PMID 35602292, 2022). "Accumulating evidence has also showed that overexpression of HCP5 can facilitate malignant cellular behaviors of tumor cells." (PMID 34187569, 2021). "Previous studies have described HCP5 as a cancer promoter in most malignancies, while the expression level of HCP5 has also been found to be downregulated in some tumor tissues." (PMID 34923990, 2021). "We observed that, compared to adjacent normal tissues, HCP5 in tumor tissues was markedly downregulated." (PMID 33613117, 2021). "Our research illuminated that, HCP5, an anti-tumor lncRNA, directly targeting miR-106b-5p, in turn, suppresses GC progression through upregulation of p21." (PMID 33613117, 2021). "It is also found the HCP5 level in GC patient tumor samples is increased compared to normal samples on GEPIA website." (PMID 33371778, 2021). "HCP5 is significantly increased in diverse tumor cells, which is highly related with prognosis, tumor formation, and metastasis." (PMID 34187569, 2021). "As we can see, HCP5 expression was prominently reduced in patients with a larger tumor size and higher Ki67 index (Ki67 >50)." (PMID 33613117, 2021). "In all, our data indicated that the anti-tumor effect of HCP5 was partially mediated by negative regulation of miR-106b-5p." (PMID 33613117, 2021). "In conclusion, our results identified HCP5, a markedly downregulated lncRNA, was relevant to tumor size and Ki67 index of GC." (PMID 33613117, 2021). "In all, our results demonstrated that HCP5 overexpression significantly restrained GC tumor growth in vivo." (PMID 33613117, 2021). "Ability of GC cells to form tumor spheres was enhanced by HCP5 overexpression and repressed by miR-3619-5p overexpression." (PMID 32300102, 2020). "Results showed that the FOLFOX treatment inhibited GC tumorigenesis in mice, and HCP5 overexpression abrogated the anti-tumor effect of FOLFOX regiment." (PMID 32300102, 2020). "In cancer, HCP5 was found to compete with tumor suppressive miRNAs and drive the expression of oncogenes." (PMID 32375397, 2020). "In summary, geniposide exerted a tumor suppressive role in DLBCL at least partially by regulating the HCP5/miR-27b-3p/MET axis." (PMID 33162801, 2020). "We found that HCP5 knockdown significantly reduced the tumor volume and weight of TNBC cell lines compared with control groups." (PMID 31215169, 2019). "Correspondingly, an immunostaining analysis of xenografted tumor tissues revealed that BIRC3 expression was also decreased in the HCP5 knockdown group." (PMID 31215169, 2019). "We found that HCP5 downregulation increased cell apoptosis, inhibited proliferation and tumor growth in vivo." (PMID 31215169, 2019). "In contrast, tumour growth, indicated by weight and volume, was significantly decreased in the si-HCP5 group." (PMID 29515098, 2018). "The PCR results showed that LINC00472, and HCP5 were downregulated in LAD tissues when compared with adjacent non-tumor lung tissues, while SNHG12 was over-expressed in LAD tissues." (PMID 28793054, 2017). "Moreover, the percentage of TUNEL-positive cells in tumor tissues was found to be notably increased by HCP5 silencing." (PMID 38071681, 2024). "Next, we wanted to investigate the HCP5 role in tumor immunity of HCC." (PMID 38643145, 2024). "Moreover, compared to those in the si-NC group, the tumor volume and tumor weight in the si-HCP5 group were notably decreased in the SKOV-3 xenograft model." (PMID 38071681, 2024).
tumor (continued). "In summary, our findings affirm that the reduction of HCP5‐132aa levels in vivo can induce ferroptosis and thereby inhibit tumor growth in GC, suggesting that HCP5‐132aa may be a promising therapeutic target for GC." (PMID 39447131, 2024). "In addition, H&E staining, immunohistochemistry, and western blotting were employed to detect the expression of HCP5‐132aa and Ki‐67 in tumor tissues from the various xenograft nude mice groups." (PMID 39447131, 2024). "Cancer metastasis is promoted by HCP5 through EMT in several tumor diseases." (PMID 35693013, 2022). "A nude mouse xenograft tumor model was carried out to detect the role of HCP5 in vivo." (PMID 35602292, 2022). "We can speculate that dysregulation of HCP5 expression in LUAD patients may lead to tumor brain metastasis by downregulating HOXA7 by affecting miR-17-5p." (PMID 35693013, 2022). "HCP5 closely contributes to tumor initiation and progression." (PMID 36248798, 2022). "HCP5 expression in tumor tissues was prominently higher than that in the normal group." (PMID 36248798, 2022). "HCP5 affects tumor progression differently depending on the type of malignancies." (PMID 35693013, 2022). "In addition, HCP5 promotes tumor growth in vivo and in vitro as well as apoptosis and proliferation." (PMID 35027621, 2022). "Silencing of HCP5 prevented tumor progression in vitro and in vivo." (PMID 35602292, 2022). "Similarly in our collected samples, the expression level of HCP5 in esophageal tissues is higher than adjacent tumor tissues." (PMID 34969363, 2022). "Due to the relatively insufficient number of patients, only tumor size has a statistical difference in comparison between high and low expression groups when analyzing the relationship between clinical characteristics and HCP5." (PMID 35399723, 2022). "In sum up, dysregulation of HCP5 expression was closely related to tumor prognosis, thus may be a potential prognostic biomarker in cancers." (PMID 34923990, 2021). "To gain insights into whether HCP5 could act as a critical role in vivo on tumor growth, we subcutaneously inoculated SGC-7901 cells stably overexpressing HCP5 into the back flank of male nude mice." (PMID 33613117, 2021). "It was speculated that HCP5 might come from the secretion of tumor cells and was mainly related to tumor metastasis." (PMID 34222007, 2021). "Moreover, a previous study reported that lncRNA HCP5 expression was significantly upregulated in GC tissues compared with those in paired non-tumor tissues." (PMID 33371778, 2021). "Our results illuminated that HCP5 could exert an anti-tumor effect in GC by suppressing abilities of GC cell invasion, migration and proliferation in vitro and restrain growth of tumor in vivo." (PMID 33613117, 2021). "Moreover, miR-29b has been identified as a negative regulatory target gene of the lncRNA HLA Complex P5 (HCP5), which plays a tumor suppressor role to prevent proliferation, migration, and invasion of HCC cells." (PMID 34771525, 2021). "Subsequently, we inoculated subcutaneously the treated SGC-7901 cells and results revealed that miR-106b-5p overexpression dramatically facilitated xenograft tumor growth, whereas HCP5 overexpression partly interdicted the effects of enhanced tumorigenicity induced by miR-106b-5p." (PMID 33613117, 2021). "Consistent with the in vitro findings, knockdown of HCP5 destroyed the HCC tumor tissues." (PMID 34148029, 2021). "Moreover, miR-29b-3p has been identified as a negatively regulatory target gene of HCP5, and served as a tumor suppressor of HCC to prevent cell proliferation, migration, and invasion." (PMID 34148029, 2021). "The HCP5 level in GC patient tumor samples is increased compared to normal samples." (PMID 33371778, 2021). "Next, tumor weight of HCP5 overexpression group was found dramatically reduced." (PMID 33613117, 2021). "To verify whether HCP5 was secreted by tumor cells, we also examined the expression of HCP5 in GES-1, MGC-803, and MKN-45." (PMID 34222007, 2021).
tumor (continued). "Several reports indicate that HCP5 exerts important roles in a variety of neoplasms." (PMID 34187569, 2021). "Moreover, tumor growth was effectively suppressed by HCP5 overexpression indicated by tumor growth curve." (PMID 33613117, 2021). "The tumor volume of the sh-HCP5 transfected group was lower than that of the control group, which further indicated that down-regulation of HCP5 could slow down HCC progression." (PMID 34148029, 2021). "HCP5 expression was significantly increased in tumor tissues compared with adjacent normal tissues." (PMID 33439936, 2021). "Down-regulation of HCP5 can promote apoptosis and inhibit tumor growth." (PMID 34375306, 2021). "Silence of HCP5 plays a tumor-repressive effect via increasing miR-128-3p in thyroid carcinoma." (PMID 34187569, 2021). "All data suggested that knockdown of HCP5 had a tumor-suppressive role in OS." (PMID 33439936, 2021). "To sum up, we believed that serum HCP5 could be regarded as a new marker for early diagnosis of GC and tumor dynamic monitoring." (PMID 34222007, 2021). "In vivo assays showed that HCP5 could abrogate the anti-tumor effect of FOLFOX regime, indicating that targeting HCP5 could be an innovative way to higher the efficacy of chemotherapy in GC." (PMID 32300102, 2020). "And HCP5 knockdown promoted apoptosis, inhibited proliferation, as well as tumor growth in vivo." (PMID 31215169, 2019). "In summary, our study revealed that HCP5 is a tumour regulator in the development of FTC and that it may contribute to improvement of FTC diagnosis and therapy." (PMID 29515098, 2018). "Moreover, immunostaining demonstrated that the expression of ST6GAL2 was up-regulated in the FTC tissues with high expression of HCP5 as well as in xenograft tumour tissues in the FTC133/HCP5 group." (PMID 29515098, 2018). "Furthermore, in the si-NC group, the glands in the tumor were irregular in shape, with epithelial atypia and pathological mitoses, and these abnormalities were markedly attenuated by HCP5 silencing, along with the increased pathological changes in tumor tissues." (PMID 38071681, 2024). "In addition, overexpressed HCP5 reversed the anti-tumor effect of TGR5 in CC." (PMID 39201624, 2024). "Moreover, alteration of HCP5 expression could regulate the characteristics of GC cells such as migration, invasion and proliferation in vitro and tumor growth in vivo." (PMID 33613117, 2021). "Our findings suggested HCP5 may be a tumor regulator in the GC progression." (PMID 33371778, 2021). "Hence, we speculated that the high expression of HCP5 in peripheral blood might be derived from the secretion of some tumor cells." (PMID 34222007, 2021). "Also, miR-29b-3p was found as a tumor suppressor and negatively regulatory factor of HCP5 in HCC." (PMID 34148029, 2021). "Additionally, knockdown of HCP5 could exert tumor-preventing effects by up-regulating miR-128-3p in anaplastic thyroid cancer." (PMID 34148029, 2021). "We speculated that upregulation of HCP5 in TNBC may promote tumor aggressive." (PMID 31215169, 2019). "We speculated that up-regulation of HCP5 may promote an aggressive tumour phenotype." (PMID 29515098, 2018). "The expression of the RUNT-related transcription factor RUNX1 is inhibited by the knockdown of HCP5, and RUNX1 binds to microRNA-139 to affect the metastasis and proliferation of tumor cells." (PMID 38071681, 2024). "Herein, the levels of HCP5 and PTBP1 were found to be markedly increased in malignant OC tumor tissues and OC cell lines." (PMID 38071681, 2024). "HCP5 facilitates cell proliferation and restrains apoptosis via miR-27a-3p/IGF-1 axis in human granulosa-like tumor cell line KGN." (PMID 36917093, 2023). "To explain the potential effectiveness of the HCP5 /hsa-miR-17-5p/HOXA7 axis in LUAD at the clinical level, we performed qRT-PCR using available tumor samples from 29 LUAD patients." (PMID 35693013, 2022).
tumor (continued). "Among them, FAM30A, HCP5, LINC00963, TMEM147-AS1, and TTTY15 indicated a worse prognosis, but LINC00342, MEG3, HCG18, and N4BP2L2-IT2 demonstrated a better tumor prognosis." (PMID 35615374, 2022). "Therefore, HCP5 could act as a tumor suppressor in GC progression." (PMID 33613117, 2021). "Concordantly, the final tumor weight and volume reduced by FOLFOX in mice were reversed by the overexpression of HCP5." (PMID 32300102, 2020). "HCP5 knockdown induced TNBC cell apoptosis, and inhibited cell proliferation and orthotopic xenograft tumor growth." (PMID 31215169, 2019). "Our data from the functional study confirmed that HCP5 promotes FTC progression by enhancing the proliferation, migration, invasiveness and angiogenic capacity of FTC cells as well as tumour growth in vivo." (PMID 29515098, 2018). "Correspondingly, an immunostaining analysis of xenografted tumour tissues revealed that ST6GAL2 and Ki67 expression was also increased in the FTC133/HCP5 group, whereas the inverse was found in the FTC238/si-HCP5 group." (PMID 29515098, 2018). "Expression of HCP5 acted as a sponge for miR-4656, preventing miR-4656 from suppressing the cell migration-inducing hyaluronidase 1 (CEMIP) gene, leading to upregulated expression of CEMIP, which plays a key role in tumour proliferation." (PMID 38052806, 2023). "In addition, the expression of both HOXA7 and HCP5 was positively correlated with FPI, suggesting a strong correlation between ferroptosis and tumor brain metastasis." (PMID 35693013, 2022). "The data of 215 samples in total were obtained from GEO database (98 normal tissues and 117 tumor tissues), and 1685 differentially expressed mRNAs (176 downregulated and 1509 upregulated) and 3 upregulated lncRNAs (MCM3AP-AS1, HCP5 and GUSBP11, all upregulated) were found." (PMID 35365175, 2022). "Negative correlation was determined between HCP5 expression level and tumor size and overall survival in GC patients." (PMID 33613117, 2021). "According to our collected human HCC data, we discovered that the expression of HCP5 was closed related with HCC tumor size, vascular invasion, and the TNM stage, which further suggested the possibility that high levels of HCP5 did have an accelerating effect in mediating the course of HCC." (PMID 34148029, 2021). "LncRNA HLA complex P5 (HCP5) was induced in TNBC cell lines and tumor tissues." (PMID 34375306, 2021). "It turned out that in both GC cells and the tumor spheres generated by GC cells, the expression of HCP5, rather than AFAP1-AS1, was upregulated under the co-culture with MSCs versus control." (PMID 32300102, 2020). "HCP5 (HLA Class I Histocompatibility Antigen Protein P5) is localised in the major histocompatibility complex (MHC) class I region and has involvement in the development of various tumours including OC." (PMID 31182053, 2019). "In this study, we found that HCP5 expression was much higher in TNBC cell lines and tumor tissues." (PMID 31215169, 2019). "In this study, we reported that HCP5 was overexpressed in tumour tissue and that this lncRNA promoted proliferation, migration, invasiveness and angiogenic ability of FTC cells as well as tumour growth in vivo." (PMID 29515098, 2018). "As expected, inflammatory response, tumor inflammation signature score, and IL-10 anti-inflammatory signaling pathway were positively correlated with HCP5 and LGALS3 in HCC, implying that the high level of HCP5 or LGALS3 expression is characterized by a high immune cell infiltration." (PMID 38643145, 2024). "However, HCP5-132aa ORF knockdown did not synergize with Erastin to significantly inhibited tumor growth, consistent with the results in vitro." (PMID 36980766, 2023). "Notably, the HCP5-132aa ORF-mut plasmid failed to induce these effects, providing further evidence that HCP5-132aa functions as a tumor promotor." (PMID 36980766, 2023).